RYR1 (ryanodine receptor 1)
Diseases named in the same sentence as RYR1 in open-access papers (continued):
Sharing a sentence is not in itself a finding about the gene and the disease.
Malignant hyperthermia (continued). "The type 1 ryanodine receptor (RyR1) is a Ca2+ release channel in the sarcoplasmic reticulum of skeletal muscle and is mutated in several diseases, including malignant hyperthermia (MH) and central core disease (CCD)." (PMID 26115329, 2015). "It should be noted that malignant hyperthermia, a disease associated with RyR1 mutations, is sensitive to potassium chloride, and therefore a testing method in patients or biopsy samples need to be initiated prior to potassium supplementation." (PMID 25564733, 2015). "RYR1 mutations associated with malignant hyperthermia (MH) and CCD are grouped in three regions of RYR1 protein or ‘hot spots’: N-terminal (residues p.M1-R614), central (p.R2163–p.R2458) and C-terminal (p.R4136-p.P4973)." (PMID 25084811, 2014). "As an example, we have mapped all the mutations in RYR2 that cause CPVT and other cardiac diseases onto RYR1, which can be used to assess novel missense variants found in patients with malignant hyperthermia or central core disease." (PMID 24136861, 2014). "Malignant hyperthermia (MH) is a fulminant pharmacogenetic disorder in which the vast majority of identified causative mutations are found in the genes encoding RyR1 or CaV1.1." (PMID 23509717, 2013). "The c.7025A>G (p.Asn2342Ser) missense on the paternal allele has been associated with malignant hyperthermia susceptibility (rs147213895), known to result from heterozygous RYR1 mutations." (PMID 23826317, 2013). "Malignant hyperthermia (MH) is a pharmacogenetic disorder most often linked to mutations in the type 1 ryanodine receptor (RyR1) or the skeletal L-type Ca2+ channel (CaV1.1)." (PMID 23509717, 2013). "A long sweep on chromosome 30 in Golden retrievers spans the RYR1 gene, involved in the skeletal muscle calcium release channel and implicated in canine malignant hyperthermia by linkage analysis." (PMID 22022279, 2011). "The porcine RYR1 gene (M91451) which had the largest number of LD-specific alternative splicing events has been associated with malignant hyperthermia and has significant effects on pig meat quality and carcass leanness." (PMID 21906321, 2011). "Interestingly, the athlete was known to have a malignant hyperthermia-associated mutation in the RyR1 gene, which suggests a link between exertional heatstroke and malignant hyperthermia; however, further detailed studies are required in the respective field." (PMID 40002675, 2025). "Mutations in RYR1, the gene encoding RyR1, underlie several neuromuscular disorders, including malignant hyperthermia (MH; MIM #145600), central core disease (CCD; MIM #11700), specific forms of multi‐minicore disease and centronuclear myopathy (MmD, CNM; MIM # 255320)." (PMID 41091627, 2025). "In this study, we performed gene panel testing on Japanese patients with confirmed or suspected malignant hyperthermia (MH) and characterized the distribution of variants supporting pathogenicity in RYR1 and CACNA1S, along with the identification of several novel variants." (PMID 40869992, 2025). "These distinctions extend to their associated disorders, with RYR2 mutations linked to cardiac arrhythmias such as catecholaminergic polymorphic ventricular tachycardia, while RYR1 mutations are typically associated with malignant hyperthermia and muscular pathologies." (PMID 40060969, 2025). "Background/Objectives: Variants in the RYR1 gene are associated mainly with Malignant Hyperthermia." (PMID 41300704, 2025).
Malignant hyperthermia (continued). "Importantly, RYR1 mutations are also associated with a predisposition to malignant hyperthermia, with gain-of-function mutations found in 50-70% of affected individuals." (PMID 41209931, 2025). "The type 1 ryanodine receptor (RyR1) is a promising candidate as a target for inhaled anesthetics because mutations of RyR1 are linked to malignant hyperthermia (MH), a potentially life-threatening pharmacological disorder induced by the use of inhaled anesthetics." (PMID 40460053, 2025). "In addition, a nonsense variant within RYR1 (rs200563280) had the next highest amount of evidence (n = 20) of pathogenicity and likely pathogenicity, with association with malignant hyperthermia susceptibility." (PMID 39354004, 2024). "Notably, two unrelated families (family 72 and 76) had a triplet of RYR1 variants in cis, which was previously linked to malignant hyperthermia susceptibility." (PMID 38982518, 2024). "RYR1 encodes the sarcoplasmic reticulum (SR) calcium release channel (or ryanodine receptor—RyR1) and its mutations are associated with susceptibility to malignant hyperthermia (MH [MIM: 145600]) and myopathies, especially congenital central core disease (CCD [MIM 117000])." (PMID 37510264, 2023). "RyR1 is the major calcium release channel protein of the skeletal muscle, and variants in RYR1 may lead to several myopathies, and the pharmacogenetic disorder Malignant Hyperthermia (MH)." (PMID 37204519, 2023). "While remimazolam does not seems to affect RyR1 directly, the IP3-dependent calcium elevation mediated by remimazolam could play a role in sensitizing RyR1 in an individual with Malignant Hyperthermia (MH) susceptibility." (PMID 35104283, 2022). "The identified RYR1 mutations (p.Thr2206Met or p.Gly2434Arg, in patient 1 and patient 2, respectively) were previously identified in individuals with malignant hyperthermia susceptibility and are reported as causative according to the European Malignant Hyperthermia Group rules." (PMID 35666680, 2022). "Moreover, RYR1 variants can cause malignant hyperthermia (MH) susceptibility, a hypermetabolic response characterized by chronic muscle contraction and elevated body temperature in response to halogenated anesthetics." (PMID 35698232, 2022). "We hypothesize that patients with a history of RYR1-related exertional rhabdomyolysis or malignant hyperthermia susceptibility do have permanent neuromuscular symptoms between malignant hyperthermia or exertional rhabdomyolysis episodes." (PMID 36751502, 2022). "We performed a prospective cross-sectional observational clinical study of neuromuscular features in patients with a history of RYR1-related exertional rhabdomyolysis and/or malignant hyperthermia susceptibility (n = 40) compared with healthy controls (n = 80)." (PMID 36751502, 2022). "Mutations to the RYR1 gene can compromise calcium homeostasis leading to a vast range of clinical phenotypes encompassing hypotonia, myalgia, respiratory insufficiency, ophthalmoplegia, fatigue and malignant hyperthermia (MH)." (PMID 35698232, 2022). "Taken together, heterozygous missense mutations affecting the RyR1 central domain have primarily been associated with suspicion of malignant hyperthermia, suggesting that p.Ser4028Leu patients may be at risk for MHS." (PMID 34535181, 2021). "Malignant hyperthermia (MH) is a rare pharmacogenetic disorder, resulting in excessive Ca2+ release from the sarcoplasmic reticulum after activation of the abnormal ryanodine receptor (RYR1 encoded by the RYR1 gene)." (PMID 33564012, 2021). "Currently more than 400 malignant hyperthermia associated variants of unknown significance in the gene coding for RYR1 have been detected." (PMID 33564012, 2021). "Patients with specific variants in RYR1 or genes encoding RyR1-associated proteins that make the SR leaky to Ca2+ are at risk of developing malignant hyperthermia (MH) under anesthesia in which volatile anesthetics trigger uncontrolled Ca2+ release and heat production." (PMID 34705503, 2021).
Malignant hyperthermia (continued). "Some dominant RYR1-RM variants are allelic to the malignant hyperthermia susceptibility trait (MHS), which is a pharmacogenetics predisposition to malignant hyperthermia and severe adverse reactions to volatile anesthetics and muscle relaxants, and some of these imply an increased risk of MHS." (PMID 34827576, 2021). "Five mutations associated with malignant hyperthermia are found in the RyR1 Repeat1–2 domain." (PMID 32899693, 2020). "Pathogenic variations in the gene encoding the skeletal muscle ryanodine receptor (RyR1) are associated with malignant hyperthermia (MH) susceptibility, a life-threatening hypermetabolic condition and RYR1-related myopathies (RYR1-RM), a spectrum of rare neuromuscular disorders." (PMID 32381029, 2020). "Indeed, CICR activity is enhanced by many RYR1 mutations found in malignant hyperthermia and central core disease and by RYR2 mutations identified in CPVT13–15." (PMID 30271978, 2018). "Another study confirmed that different genotypes of RYR1 gene mutations may lead to two kinds of skeletal muscle genetic diseases: malignant hyperthermia and central core disease, both of which are autosomal dominant genetic diseases." (PMID 30027098, 2018). "The approach may enable characterizing new CPVT mutations found in patients, but possibly also mutations of RyR1, which are associated with malignant hyperthermia or central core disease." (PMID 29235522, 2017). "Furthermore, mutations in RyR1 gene encoding the skeletal muscle isoform of the ryanodine receptor (RyR1) cause malignant hyperthermia (MH) and central core disease (CCD)." (PMID 27430885, 2016). "Recent studies in mammalian systems have shown that the skeletal muscle ryanodine receptor/Ca2+-release channel RyR1 is subject to S-palmitoylation modification in ''hot spot'' regions containing sites of mutations implicated in malignant hyperthermia and central core disease." (PMID 27058039, 2016). "The first category of RyR1 mutations cause a higher probability of activation of RyR1 by muscle fiber electrical depolarization or by RyR1 activators, and are manifested in the malignant hyperthermia (MH) phenotype." (PMID 26793121, 2015). "Thus initially RYR1 mutations were described in individuals susceptible to malignant hyperthermia (MHS)." (PMID 25476234, 2014). "CCD is due to mutations in the skeletal muscle ryanodine receptor (RYR1) gene at chromosome 19q13.1, also implicated in the malignant hyperthermia susceptibility (MHS) trait, initially recognised as a familial autosomal dominant trait by Denborough and Lovell in Australia." (PMID 17504518, 2007). "Notably, the D179N mutation has been linked with CPVT and the equivalent RyR1 residue (D166G and D166N) has been linked with malignant hyperthermia, further highlighting the pivotal involvement of the negatively charged side chain of this residue in N-terminus self-association." (PMID 32077934, 2021). "Autosomal dominant RYR1 mutations have a variable age of onset, ranging from birth to the 6th decade of life and are associated with a variable phenotypic spectrum including malignant hyperthermia susceptibility, rhabdomyolysis, proximal weakness and possibly mild facial weakness." (PMID 32456280, 2020). "An increased sensitivity to 4-CmC has been linked to patients with malignant hyperthermia and ratiometric calcium imaging has been used to show hypersensitivity of 4-CmC in muscle cells from a patient with a mutation in RyR1 associated with malignant hyperthermia susceptibility." (PMID 25564733, 2015). "Central Core Disease (CCD) and Malignant Hyperthermia (MH) are autosomal dominant skeletal muscle disorders linked primarily to single amino acid substitutions in the sarcoplasmic reticulum Ca2+ release channel of skeletal muscle (the type 1 ryanodine receptor or RyR1)." (PMID 23152933, 2012).
Malignant hyperthermia (continued). "A genetic examination was performed in both patients, proving that the patient with CKD has a genetic defect in the RYR1 gene, which is observed in patients with malignant hyperthermia." (PMID 40429823, 2025). "Among these cases was also an individual with an increased risk of malignant hyperthermia (OMIM #145600, RYR1 gene)." (PMID 40620702, 2025). "Abnormal SR Ca2+ release due to missense mutations in RYR1 and RYR2 results in neuromuscular (e.g., malignant hyperthermia, MH) and cardiac disease (e.g., catecholaminergic polymorphic ventricular tachycardia, CPVT), respectively." (PMID 36311249, 2022). "Of note, CPIC has also developed guidelines for germline variants of RYR1 and CACNA1S, presenting clinically as malignant hyperthermia (inherited, familiar syndrome)." (PMID 35685436, 2022). "Of these, dantrolene is the only specific RYR1 antagonist that is approved by FDA for the treatment of malignant hyperthermia." (PMID 35953818, 2022). "Abnormal RyR1 activity compromises normal muscle function and results in various human disorders including malignant hyperthermia, central core disease, and centronuclear myopathy." (PMID 34535181, 2021). "RYR1 gene has originally been reported to be responsible for congenital myopathy and malignant hyperthermia." (PMID 31068157, 2019). "In myotubes expressing malignant hyperthermia RyR1 cDNAs, myoplasmic Ca2+ is elevated due to a significant passive Ca2+ leak from the SR." (PMID 25564733, 2015). "Mutations in the gene encoding ryanodine receptor type-1 (RYR1), the calcium ion (Ca2+) release channel in the sarcoplasmic reticulum (SR) of skeletal muscle, are linked to central core disease (CCD) and malignant hyperthermia (MH) susceptibility." (PMID 26075051, 2015). "RyR1 mutations in humans are associated with several congenital myopathies including CCD, multi-mini core disease, hypokalemic periodic paralysis, and malignant hyperthermia (MH)." (PMID 25564733, 2015). "Among five amino acids involved in hydrogen bond interactions between the RyR1 EF hand and S2–S3 domains, R4736 was reported to be associated with malignant hyperthermia." (PMID 38159862, 2023). "Malignant hyperthermia susceptibility (MHS) has been found as an autosomal dominant trait, largely arising from the mutation of the ryanodine receptor type 1 gene that encodes RYR1." (PMID 35692882, 2022). "Malignant hyperthermia susceptibility was also significantly correlated with RYR1 mutations, so whether ATP2A1 is correlated with RYR1 is worth discussing." (PMID 35692882, 2022). "Therefore, the variant classifies as likely pathogenic based on both MHS/RYR1-specific adaptation of the ACMG criteria, and the genetic scoring matrix from The European Malignant Hyperthermia group." (PMID 34462577, 2021). "In the RyR1 SPRY2 domain, a total of five mutations have been identified: three of them are associated with CCD (R1075W, G1165D, and R1179W) and two with malignant hyperthermia (R1127H and R1140C)." (PMID 32899693, 2020). "In addition, RyR1 mutations in muscle cause diseases such as multi-mini core disease (MMD), hypokalemic periodic paralysis, and malignant hyperthermia (MH), although the phenotype/genotype relationship is unclear." (PMID 25564733, 2015). "However, CACNG1, CACNB1 and CACNA2D1 encode for subunits of the DHPR calcium channel, which is in direct contact and regulating RYR1 in skeletal muscle, and one mutation in the channel subunit CACNA1S of DHPR was linked to malignant hyperthermia." (PMID 25353622, 2014).
Malignant hyperthermia (continued). "Several compounds are known to modulate RYR1 activity, among which dantrolene, a specific blocker of RYR1 and RYR3, was the only one approved by FDA for the treatment of diseases like malignant hyperthermia (MH), and central core disease (CCD)." (PMID 35953818, 2022). "A weakness of this study is that the screens were conducted on models that completely lack expression of RyR1, whereas none of the patients with malignant hyperthermia or RyR1-related myopathies are nulls." (PMID 32372758, 2020). "Pathogenic variants in RYR1 are known to be associated with autosomal dominant and autosomal recessive central core disease (CCD) (OMIM 117000), and malignant hyperthermia (OMIM 145600) but have not been associated with HL." (PMID 29293505, 2018).